RN7SL775P (RNA, 7SL, cytoplasmic 775, pseudogene)
Gene: Miscellaneous RNA gene on chromosome 17 (17,178,414 to 17,178,749, forward strand). Ensembl gene ENSG00000243370.
Homologues: Orthologues: chimpanzee Metazoa_SRP (99% identical), macaque Metazoa_SRP (93% identical). Paralogues in human: RN7SL33P (79% identical), RN7SL526P (73% identical), RN7SL487P (71% identical), RN7SL40P (70% identical), RN7SL317P (70% identical), Metazoa_SRP (69% identical), Metazoa_SRP (68% identical), RN7SL2 (68% identical), RN7SL733P (67% identical), Metazoa_SRP (67% identical), RN7SL1 (67% identical), RN7SL326P (66% identical), and 704 more.